OR4F6 (olfactory receptor family 4 subfamily F member 6)
Description:
Odorant receptor.
Synonyms: OR4F12; OR15-15
Tractability: Antibody: UniProt places it where antibodies can reach, with medium confidence; UniProt predicts a signal peptide or a membrane-spanning region; its Gene Ontology location is reachable by antibodies, with medium confidence.
Gene: Protein-coding gene on chromosome 15 (101,803,509 to 101,806,887, forward strand). Ensembl gene ENSG00000184140.
Subcellular location: Cell membrane
Pathways (Reactome):
Sensory Perception: Expression and translocation of olfactory receptors
Gene Ontology:
Molecular function: olfactory receptor activity; G protein-coupled receptor activity
Biological process: detection of chemical stimulus involved in sensory perception of smell; G protein-coupled receptor signaling pathway
Cellular component: plasma membrane; membrane
Genetic constraint (gnomAD): Loss-of-function variants: 13 observed, 16.2 expected, observed/expected ratio (o/e) 0.8, 90% interval 0.52 to 1.27. The upper end of that interval is the gene's LOEUF score, 1.27, which puts it in group 5 of 6, group 1 being the genes least tolerant of losing a copy. Missense variants: 414 observed, 377.62 expected, observed/expected ratio (o/e) 1.1, 90% interval 1.01 to 1.19. Synonymous variants: 149 observed, 138.77 expected, observed/expected ratio (o/e) 1.07, 90% interval 0.94 to 1.23.
Homologues: Orthologues: chimpanzee OR4F6 (99% identical), macaque OR4F6 (95% identical), mouse Or4f6 (85% identical), rat Or4f6 (84% identical), rat Or4f6b (79% identical), rabbit OR4F6 (75% identical). Paralogues in human: OR4F15 (71% identical), OR4F16 (67% identical), OR4F29 (67% identical), OR4F3 (67% identical), OR4F21 (67% identical), OR4F5 (59% identical), OR4F4 (58% identical), OR4F17 (57% identical), OR4K15 (56% identical), OR4K5 (55% identical), OR4K1 (54% identical), OR4K17 (54% identical), and 116 more.